PPARG (peroxisome proliferator activated receptor gamma)
Diseases named in the same sentence as PPARG in open-access papers (continued):
Sharing a sentence is not in itself a finding about the gene and the disease.
tumor (continued). "Several publications demonstrated that PPARγ activation suppresses COX-2 expression and a dual sEH/PPARγ could potentially circumvents the tumor promoting effects of (COX)-derived metabolites of EETs." (PMID 33776749, 2020). "PPARG was involved in controlling angiogenesis, tumor progression and metastasis." (PMID 33083004, 2020). "Highly expressed PPARG tumor cells were more resistant to carboplatin (correlation coefficient = −0.422, p < 0.001), cisplatin (correlation coefficient = −0.396, p = 0.002), arsenic trioxide (correlation coefficient = −0.419, p < 0.001), and lomustine (correlation coefficient = −0.410, p = 0.001)." (PMID 33029111, 2020). "Thus, miR-27b-3p and PPARG can act either as oncogenes or tumor suppressors depending on the cell type." (PMID 32850439, 2020). "Recently, PPARγ has emerged as a mediator of tumor microenvironments." (PMID 33266062, 2020). "Results from the PEA and PPI analysis suggested that PPARG might inhibit the development of LA through the regulation of tumor cell proliferation and transmission-related molecules, including an LA tumor cell suppressor MIR145." (PMID 32395124, 2020). "In addition, the in vitro tumor suppressive function of PPARγ was confirmed using orthotopic and heterotopic xenograft mouse models." (PMID 32280134, 2020). "Notably, chimeric mice with iNKT cell-specific deletion of PPARγ exhibited larger tumor size and lower survival than their wide type controls in response to PIO plus αGC treatments." (PMID 31974378, 2020). "By contrast, in MDSCs, PPARγ activation dampens immunosuppression and tumor progression." (PMID 32823961, 2020). "Sporadically, the tumor-promoting side of PPARG was observed in some cancers; it is easy to infer that the precise effects of PPARG and its agonists might depend on types of cancers and tumor environment." (PMID 33029111, 2020). "In addition, most of previous studies have revealed that PPARγ acts as a tumor suppressor in BC, inhibiting cell proliferation and inducing apoptosis in different in vivo and in vitro models." (PMID 32085795, 2020). "In addition, dietary supplementation with n-3 PUFAs was found to increase PPARγ protein content, concomitantly with a reduction of tumor burden in rats with induced mammary carcinogenesis." (PMID 32224850, 2020). "The results of our study are also consistent with these results, which support the hypothesis that the PPARγ gene is a tumor suppressor gene, and that dysfunction of PPARγ contributes to tumorigenesis." (PMID 33197888, 2020). "However, evidence suggests that PPARγ does not initiate tumor formation in normal breasts whereas in a tumor environment, the expression of PPARγ results in tumor progression signaling." (PMID 32796696, 2020). "The following results indicated the PPARγ expression was possibly correlated with tumor size, clinical stage, pathological grade and recurrence, and may be involved in progression of patients with UC after RT." (PMID 33289586, 2020). "PPARγ expression was correlated with tumor size, clinical stage, pathological and recurrence." (PMID 33289586, 2020). "Moreover, similar to CDK5, pho‐PPARγ expression was mainly detected in the tumor tissues, especially in those of the late‐stage, as well as the lymph node with metastasis." (PMID 33240752, 2020). "Endogenous or synthetic PPARγ agonists may offer leads to novel strategies that target both epithelial neoplastic cells and the tumor microenvironment." (PMID 31936729, 2020). "In addition to regulating the oncogenic activities of cancer cells, PPARγ can control the tumor microenvironment, affecting multiple aspects of the cancer-associated inflammatory responses." (PMID 31936729, 2020). "PPARγ expression was negatively correlated with tumor size, clinical stage, pathological grade, and tumor recurrence, which could be used as a candidate biomarker for UC detection after RT." (PMID 33289586, 2020).
tumor (continued). "Interestingly, the consensus peaks that were specifically H3K4me1-positive in the luminal tumours were enriched for Peroxisome proliferator-activated receptor gamma (PPAR-γ or PPARG) and Retinoid X Receptor Alpha (RXRA) binding motifs." (PMID 32616859, 2020). "A hypothesis could be a potential role of Cox-1 in nucleocytoplasmic translocation of PPARγ, thereby suppressing tumor growth." (PMID 32085795, 2020). "Stratified analyses between PPARG rs3856806 C>T polymorphism and CRC risk by site of tumor." (PMID 30838172, 2019). "Importantly, the well characterized PPARγ agonist rosiglitazone suppresses the ability of systemic UV-IS to suppress CHS responses as well as the ability of UVB treatment to promote B16F10 tumor growth." (PMID 31212694, 2019). "In particular, PPARγ, PTEN, and CD36 expression in F4/80-positive cells (red) was also markedly enhanced by apoptotic cell injection, which reflects apparent PPARγ, PTEN, and CD36 induction in tumor-associated macrophages (TAMs), as the F4/80-positive macrophage intensity was not different." (PMID 30842627, 2019). "Our observations share some similarities with those of another group that provides evidence that PPARγ activation may promote anti-tumor immune responses." (PMID 31212694, 2019). "We detected a comparable PPARG mutation rate, 3.1% of the tumors (14/455), but a higher RXRA mutation rate, 6.1% of the tumors (28/455) in these tumor series compared to the previous tumor series analyzed." (PMID 30651555, 2019). "PPARG can exhibit anti-tumor effects both by PPARG dependent and independent pathways." (PMID 31263479, 2019). "One possible explanation of this debate is that activation of PPARγ induces growth inhibition in epithelial cancer cells, whereas it triggers tumor growth in stromal cells, indicating that the consequences of PPARγ activation for tumorigenesis are dependent on the cellular compartment." (PMID 31138783, 2019). "Unlike PPARγ, which is associated with anti-tumor effects upon ligand binding, PPARβ/δ in CAFs has a pro-tumor action." (PMID 30925918, 2019). "Also, PPARG agonist can cross blood brain barrier and has been proven beneficial in reducing tumor in human xenograft model." (PMID 31263479, 2019). "Thus dmrFABP5 produced significant (Student t-test, p < 0.0001) reduction in the staining intensity of p-PPARγ in the tumour cells by 67%." (PMID 31258834, 2019). "In contrast, the expression of PPARγ was significantly decreased in the tumor tissues." (PMID 30845932, 2019). "Accordingly, activation of PPARγ in CAFs could potentially act as a tumor suppressor by modifying the activation and supportive properties of CAFs in cancer development." (PMID 30925918, 2019). "Thus, downregulation of PPARG is followed by a β-catenin upregulation and it was shown that deregulation of the balanced expression of PPARs and β-catenin can influence tumor growth, cell proliferation, cell invasiveness and angiogenesis." (PMID 30568936, 2018). "Our previous review described that PPARγ has tumor-promoting activity through the upregulation of β-catenin and c-Myc expression, upregulation of COX-2, upregulation of the expression of vascular endothelial growth factor (VEGF) and VEGF receptors, and upregulation of MMP-1." (PMID 29599799, 2018). "Peroxisome proliferator activated receptor gamma (PPARγ) agonists may exhibit anti‐tumor activity by transactivating genes which are closely associated with cell proliferation, apoptosis, and differentiation." (PMID 29573196, 2018). "Recently, increasing evidence has indicated that PPARγ acts as a tumor promoter." (PMID 29599799, 2018). "Therefore, it is also conceivable that downregulation of differentiation markers (in RD and CRL2061) and the cell cycle arrest after FH535 treatment followed by apoptosis induction are rather mediated by PPARG in the RMS tumor cells than by β-catenin." (PMID 30568936, 2018). "This review briefly introduces the action mechanisms of PPARγ as a tumor promoter." (PMID 29599799, 2018).
tumor (continued). "The abundance of PPARγ could be one factor accounting for the tumor- and endothelium-specific anti-proliferation effects." (PMID 29932104, 2018). "Noteworthy, the insertion of mutations within the PPARγ gene established greater tumor aggressiveness in PTEN-deleted mice than in mice without insertion." (PMID 29966227, 2018). "It is also interesting to examine whether zaltoprofen can selectively activate not only PPARγ, but also PPARα or PPARδ, in terms of the anti‐tumor effects of zaltoprofen." (PMID 29573200, 2018). "The activation of PPARγ can induce tumor cell apoptosis via several different pathways." (PMID 29642873, 2018). "We further explored whether slc10a2 via PPARγ plays an important role in tumor suppressor with the treatment of bexarotene." (PMID 29642873, 2018). "Both roles of PPARγ are strictly tumor tissue-dependent and tumor microenvironment-dependent." (PMID 29966227, 2018). "PPARγ activation seems to act on the tumor environment, especially on inflammation." (PMID 29706964, 2018). "In addition, overexpression of PPARγ was shown to inhibit cell proliferation and tumor growth via degradation of NF-κB by acting as an E3 ligase." (PMID 29599799, 2018). "A long way of failures accompanied the introduction of PPARγ agonists in tumor therapy." (PMID 30424016, 2018). "PPARγ and PPARβ/δ are able to regulate the final fate of macrophages in a tumor environment." (PMID 29966227, 2018). "Moreover, cell line expression studies indicate co-expression of PNR and PPARγ in cells of tumor origin." (PMID 28300834, 2017). "Since colony formation represents an important trait of both normal and tumor stem cells, we subsequently tested whether PPARG inhibition affects the ability of AML cells to form single‐cell‐derived colonies." (PMID 28275008, 2017). "Moreover, in CRC cells, high levels of cannabinoids induced up-regulation of CB1-receptor through co-localization of PPARγ and RXRα at its promoting region, suggesting a potential epigenetic modulation in cannabinoid-mediated anti-tumor effects." (PMID 29354056, 2017). "This study suggests modulation of lipid metabolism could be an important biochemical feature for tumor suppressive function of PPARγ." (PMID 29137280, 2017). "Of note, PPARG expression was not limited to adipocytes, but rather noted in all cellular components of the tumor, including the undifferentiated component, where strong nuclear staining could be seen." (PMID 28275008, 2017). "Overwhelmingly, PPARγ-associated expression was significantly anti-correlated with the immune signature hinting at the possibility that tumor-autonomous PPARγ activity may suppress cytokine secretion and immune cell infiltration." (PMID 28740126, 2017). "Microarray analysis demonstrated tumor growth in vivo to involve robust PPARG‐pathway activation." (PMID 28275008, 2017). "Importantly, normal kidney cells were completely unaffected by PPARG inhibition, implying specific targeting of tumor cells." (PMID 28275008, 2017). "Collectively, our findings suggest that the PPARγ/RXRαS427F/Y pathway in tumor cells might influence the activity/localization of host immune cells and potentially blunt response to immunotherapy." (PMID 28740126, 2017). "Therefore, liganded PPARγ sumoylation is not only critical for cellular lipid metabolism but also induces oxidative stress that contributes to tumor suppressive function of PPARγ." (PMID 29137280, 2017). "Increasing literatures show that PPARα or PPARγ can inhibit tumor progression by multiple pathways, which can be the potential therapeutic targets for cancer treatment, while some agonists suppress tumor progression in a PPARα/γ- independent manner." (PMID 28948004, 2017). "Thus, it was now possible to pharmacologically manipulate tumor lineage by inhibiting PPARγ, and in essence achieve a synthetic lethal effect to endocrine therapy." (PMID 28881566, 2017).
tumor (continued). "Thus, PPARγ appears to function as a tumor suppressor that controls cell survival and differentiation within normal prostate epithelium." (PMID 29181019, 2017). "Potentially, VEGF-A may also be enhanced by PPARγ in bladder tumor tissue consequently enhancing tumor growth and migration through angiogenesis." (PMID 28348577, 2017). "In addition to regulating the oncogenic activities of cancer cells, PPARγ can control the tumor microenvironment; the receptor creates a hostile environment for tumor growth and metastasis via multiple mechanisms." (PMID 28316613, 2017). "The last part of this study was addressed to help us understand how the activation or inhibition of the autophagic pathway and PPARγ might interfere with specific tumor properties, such as survival, proliferation and aggressiveness." (PMID 28932171, 2017). "Although it is unclear why PPARG was selected as a therapeutic target in these studies, it has been previously proposed that PPARG activation may promote tumor survival by converting toxic fatty acids into inert triglycerides." (PMID 28275008, 2017). "Thus, RXRAS427F/Y and PPARG-Amp represent an expanding list of tumor cell-intrinsic “immuno-oncogenes” that promote tumorigenesis through modulating the immune microenvironment." (PMID 28740126, 2017). "However, C/EBPδ, C/EPBα and PPARγ expression, which were all elevated in the skeletal muscles of tumor-bearing animals before and after chemotherapy in our study, are involved in both lipogenesis and adipogenesis in skeletal muscle." (PMID 28832677, 2017). "We confirm that glucose restriction contributes to tumor progression since the GSCs grown at low glucose levels were higly proliferating and paralleled by a significant increase of PPARα and decrease of PPARγ, thus confirming the opposite role of the two nuclear transcription factors in GSCs." (PMID 29312541, 2017). "Mechanistically, we demonstrated that sumoylation of PPARγ is necessary for the receptor-mediated intracellular lipid biosynthesis, leading to cellular NADPH reduction and thus ROS increase, which may contribute to tumor suppressive function of PPARγ." (PMID 29137280, 2017). "This discrepancy may be related with in vivo effects of “tumor interactions”, PPARγ activation magnitude, and PPARγ-independent effects of agonists." (PMID 27323819, 2016). "Some studies demonstrated that PPARγ and its agonist rosiglitazone may have opposing effects on tumor progression, with anti-tumorigenic effects on cancer cells, but pro-tumorigenic effects on cells of the microenvironment." (PMID 27783989, 2016). "To determine if PPARγ-deficient macrophages regulate cancer cell behavior in the absence of other components in the tumor microenvironment such as fibroblasts and extracellular matrix, we performed macrophage and cancer cell co-culture experiments in vitro." (PMID 27692066, 2016). "Thus, in terms of how macrophage PPARγ impacts tumor progression, only the phenotype speaks of the truth." (PMID 27692066, 2016). "PPARγ activation can also hamper cell proliferation and tumor growth and promote apoptosis." (PMID 27698657, 2016). "Positive signals for PPARγ were obtained in the nucleus of the tumor cells." (PMID 27401457, 2016). "Importantly, Gpr132 deletion abolishes the cancer regulation by macrophage PPARγ or rosiglitazone, indicating that Gpr132 is an essential mediator of PPARγ functions in macrophages and tumor progression." (PMID 27692066, 2016). "Research to date indicates that PPARγ activation hinders tumor development and progression by modulating the differentiation, proliferation, apoptosis, and motility of cancer cells and by making the tumor microenvironment less hospitable for tumor growth and metastasis." (PMID 27698657, 2016). "Here we assess whether the disruption of PPARγ function by expression of dnPPARγ in myeloid cells has similar effect on tumor cell growth and metastasis in vivo and tumor cell proliferation and migration in vitro." (PMID 26625314, 2016).
tumor (continued). "Furthermore, in the myeloid-specific dominant-negative PPARγ (dnPPARγ) overexpression bitransgenic mouse model, tumor growth and metastasis were enhanced, and MDSCs from these mice stimulated tumor cell proliferation and migration." (PMID 26625314, 2016). "Although our co-culture experiments suggest that tumor cell-macrophage contact is required for macrophage PPARγ regulations, other possible mechanisms may exist." (PMID 27692066, 2016). "Yu and colleagues found increased DEN-induced HCC in mice lacking one PPARγ allele, thus suggesting a tumor-suppression function for PPARγ." (PMID 28115925, 2016). "Besides the regulation of adipogenesis and lipid metabolism, extensive research has also established the role of PPARγ in tumor progression and cancer metastasis." (PMID 26820738, 2016). "Importantly, these studies reveal the critical role of LAL and PPARγ in checking MDSC functions and the potential as a therapeutic target to modulate tumor growth and spread associated with MDSCs." (PMID 26625314, 2016). "Interestingly, although Tie2-g-KO mice harbored more complete PPARγ deletion than Lyz-g-KO mice and both mouse models showed enhanced tumor growth and tumor macrophage recruitment, the phenotype was more pronounced in Lyz-g-KO." (PMID 27692066, 2016). "Extensive studies have shown that PPARγ could regulate lipid metabolism and cell inflammation, and that it also has a significant anti-tumor effect." (PMID 27531890, 2016). "For example, macrophage levels of PPARγ and Gpr132 may predict not only tumor aggressiveness but also the pharmacological responses to rosiglitazone or Gpr132 inhibitors." (PMID 27692066, 2016). "Consistent with the unclear role of PPARγ in tumor samples, TZDs showed variable effects in vivo." (PMID 25866814, 2015). "Among PPARγ-WT tumours, the variable pattern may reflect alternative pathways acquired during tumourigenic progression of initiated cells, some of which may silence PPARγ expression." (PMID 25889730, 2015). "PV could act via nuclear genomic actions to suppress the transcription activity of tumor suppressors such as the peroxisome proliferator-activated receptor γ (PPARγ)." (PMID 25924236, 2015). "Given Cox-2 expression was lower in DMBA + ROSI-treated PPARγ-WT tumours suggests MG cell-specific PPARγ activation may play a role in suppressing Cox-2 protein levels, which is similar to our findings with respect to mammary secretory epithelial-PPARγ." (PMID 25889730, 2015). "Notably, PPARγ is known to serve as a tumor promoter in the mammary gland leading to tumor development." (PMID 26275572, 2015). "It has been suggested that increased PPARγ suppresses cell proliferation of various tumor entities." (PMID 26485029, 2015). "In ovarian cancer, however, PPARγ levels independent from tumor differentiation are increased." (PMID 25866814, 2015). "In addition, studies have shown that ligand-activated PPARγ results in G1-phase arrest and inhibits cell proliferation by affecting the G1/S checkpoint of various tumor cell lines." (PMID 24944709, 2014). "Additionally, amount of studies also confirmed that PPARγ plays a critical in tumor proliferation and differentiation, apoptosis, invasion, angiogenesis and metastasis." (PMID 24603556, 2014). "Meanwhile, PPARγ is essential for tumor proliferation, invasion and metastasis." (PMID 24603556, 2014). "Previous studies have identified that the activation of PPARγ may inhibit proliferation and reduce the invasiveness of tumor cells by blocking PI3K/Akt by upregulating the expression of PTEN." (PMID 24944709, 2014). "In this work we explore whether telmisartan could exert anti-tumor effects through PPARγ activation in A549 cells." (PMID 24603556, 2014). "Pparγ has been shown to promote the transcription of tumor-suppressor genes like Pten and Brca1." (PMID 25176219, 2014).